ENSG00000285382 (novel protein)
Gene: Protein-coding gene on chromosome 20 (32,632,183 to 32,743,567, reverse strand). Ensembl gene ENSG00000285382.
Genetic constraint (gnomAD): Loss-of-function variants: 22 observed, 27.75 expected, observed/expected ratio (o/e) 0.79, 90% interval 0.56 to 1.13. Missense variants: 187 observed, 201.52 expected, observed/expected ratio (o/e) 0.93, 90% interval 0.82 to 1.05. Synonymous variants: 74 observed, 72.71 expected, observed/expected ratio (o/e) 1.02, 90% interval 0.84 to 1.24.